HDAC6 (histone deacetylase 6)
Diseases named in the same sentence as HDAC6 in open-access papers (continued):
Sharing a sentence is not in itself a finding about the gene and the disease.
cancer (continued). "Disruption of the physiological expression and function of HDAC6 affects tumorigenic modifications, cancer cell growth, mitosis, invasion, and migration." (PMID 37373187, 2023). "Specifically, it has been reported that RUNX2 in cancer cells can recruit HDAC6 to suppress transcription." (PMID 37754231, 2023). "Among HDAC6 substrates, α-tubulin is widely known to be involved in the modulation of several cancer signaling pathways via its PTM process, including acetylation." (PMID 36639650, 2023). "The unique structure and gene targets of the HDAC6 enzyme lends itself to specific inhibitors and several specific HDAC6 inhibitors have been developed as anti-cancer agents in clinical trials (clinicaltrials.gov NCT03008018, NCT02935790, NCT01323751)." (PMID 37528157, 2023). "The overexpression of HDAC6 has been observed in many types of cancers, such as oral squamous cell carcinoma, acute myeloid leukemia, ovarian cancer and hepatocellular carcinoma." (PMID 36986673, 2023). "A selective inhibitor targeting the domains of HDAC6 has been effective in inhibiting cell growth and cancer progression while also increasing the sensitivity of transformed cells to anticancer agents." (PMID 37461108, 2023). "Evidently, HDAC6 inhibition suppressed cancer cell migration as a result of an increase in acetylated α-tubulin." (PMID 36639650, 2023). "In CAL27 human oral cavity squamous cell carcinoma cells and pharyngeal Detroit562 cells, the HDAC6 inhibitor ricolinostat increases ROS and cytotoxicity to cancer cells." (PMID 36749475, 2023). "Accumulating studies have shown that HDAC6 is overexpressed in numerous cancers and correlates with cancer prognosis." (PMID 36639650, 2023). "This study first reported that cytoplasmic GRP78 regulates ERK activity in a microtubule-dependent manner, which reveals an oncogenic role of HDAC6, filling the research gap in cancer cell biology." (PMID 36639650, 2023). "Selectively targeting HDAC6 also blocks CXCL1 signalling to advance anti-cancer therapy by repressing tumour invasion and migration." (PMID 36810912, 2023). "The current theoretical work was performed to explore the virtual repurposing of the FDA-approved drugs as inhibitors against these two (VISTA and HDAC6) cancers therapeutic targets." (PMID 37660065, 2023). "Histone deacetylase 6 (HDAC6) inhibition is an attractivestrategyfor treating numerous cancers, and HDAC6 catalytic inhibitors arecurrently in clinical trials." (PMID 37499118, 2023). "Several selective HDAC6 inhibitors are in the clinic for the treatment of cancer and solid tumors such as Ricolinostat, Citarinostat and KA-5407." (PMID 36595522, 2023). "It is probable that HDAC6 helps cancer cells escape senescence surveillance to display aggressive phenotypes." (PMID 36834846, 2023). "Results from these studies clearly demonstrate the advantage of this inhibitor over LSD1 or HDAC6 inhibitor in the treatment of a subset of cancers." (PMID 36595522, 2023). "Overexpression of HDAC6 correlates with tumorigenesis, and inhibitors of HDAC6 were proposed as anti-cancer therapeutic approaches." (PMID 37510333, 2023). "Overall, the two drugs Bexarotene and Oxymorphone revealed the strong binding affinity toward the cancer drug targets HDAC6 and VISTA." (PMID 37660065, 2023). "Selective inhibition of HDAC6 induces DNA damage, suppresses tumour proliferation and sensitises transformed cells to anti-cancer agents." (PMID 36810912, 2023). "Some previous studies showed that HDAC6-mediated tubulin deacetylation also promoted microtube stabilization and cancer progression." (PMID 34508164, 2022). "SAR studies conducted against a panel of 60 cancer cell lines clearly demonstrated the selectivity and potency of most of the derivatives against PI3Kγ, δ, and HDAC6 enzymes." (PMID 35408693, 2022). "HDAC6 inhibitors (HDAC6i) are currently in clinical trials for other cancers and show potential beneficial effects against tumor cell survival in vitro and in vivo." (PMID 36012642, 2022).
cancer (continued). "HDAC6 plays an important role in cancer, neurological diseases, inflammatory diseases, and other diseases." (PMID 35652048, 2022). "Abnormal expression of HDAC6 is correlated with neurodegenerative diseases, cardiovascular diseases, and cancer." (PMID 35955780, 2022). "For more than a decade, HDAC6 has been studied as a promising target for cancer metastasis amongst the human histone deacetylases (HDACs)." (PMID 36559094, 2022). "With its multifaceted roles, HDAC6 is an obvious therapeutic target that needs to be investigated thoroughly as a cancer treatment option." (PMID 36012642, 2022). "The identification of the domain of HDAC6 critical for binding to partner of HDAC6 is necessary for designing HDAC6-targeting anti-cancer drugs." (PMID 36076996, 2022). "Mechanisms of HDAC6-promoted anti-cancer drug resistance, cancer cell proliferation, and autophagy are discussed." (PMID 36076996, 2022). "Based on its role in autophagy and anti-cancer drug resistance, HDAC6 can serve as a target for developing single or combined treatments for cancer." (PMID 36076996, 2022). "HDAC6 functions in cancer-related processes such as tumorigenesis, angiogenesis, metastasis, the aggresome–autophagy pathway and inflammation as detailed in previous review articles." (PMID 36012642, 2022). "Based on the experiments using zebrafish model, 8b is disclosed as a novel pan-HDAC inhibitor with superior anti-cancer and anti-metastatic properties, in contrast to selective HDAC6 inhibitor 9b." (PMID 36559094, 2022). "Investigations into the mechanism of the regulation of HDAC6 expression are necessary for a better understanding of HDAC6-promoted autophagy and anti-cancer drug resistance." (PMID 36076996, 2022). "HDAC6 inhibition enhanced the sensitivity of cancer cells to anti-PD-L1 blockade by reducing the number of M2 macrophages." (PMID 36076996, 2022). "The present study further characterizes the mechanisms involved in hypoxia-induced cancer cell invasion using in vitro, in vivo and in silico approaches and identifies a HDAC6- SMAD3 pathway that can be pharmacologically targeted to inhibit tumor progression." (PMID 35681731, 2022). "The effects of combination therapy, which includes HDAC6 inhibitors, on the sensitivity of cancer cells to chemotherapeutics and immune checkpoint blockade are presented." (PMID 36076996, 2022). "HDAC6 is currently being aggressively pursued as a therapeutic target for multiple indications, including cancer and neurodegenerative diseases, by virtue of its ability to regulate processes such as protein turnover and mitochondrial transport." (PMID 35575093, 2022). "In the present study, we described how hypoxia selectively induced the pro-invasive arm of TGFβ signaling through activation of a HDAC6- SMAD3-SARA-ITGB2/VIM pathway that contributes to the ability of cancer cells to invade and form metastases." (PMID 35681731, 2022). "In particular, we propose novel regulatory roles of HDAC6 in tumorigenesis and cancer cell survival via the regulation of EGFR/Akt pathway activation." (PMID 35110592, 2022). "TargetScan analysis can predict miRNAs that target HDAC6, and these microRNAs can be anti-cancer drugs." (PMID 36076996, 2022). "Abnormal expression of HDAC6 contributes to the pathological mechanisms of a variety of malignant tumors." (PMID 35449808, 2022). "The identified mechanism involves a hypoxia-induced HDAC6-SARA-SMAD3- axis that contributes to the ability of cancer cells to degrade the extracellular matrix and form metastases." (PMID 35681731, 2022). "The current study determined the role of HDAC6 in tumor metabolism and tumor immunity through a multi-database pan-cancer analysis." (PMID 34485153, 2021). "The tubulin deacetylase SIRT2 has also been associated with autophagy regulation in several cancer cell lines, although its impact on cancer autophagy is less well understood, in comparison with HDAC6." (PMID 35008169, 2021).
cancer (continued). "Here the results were reversed, and the expression of HDAC6 in the integrated database for pan-cancers was low, contrary to recent findings." (PMID 34485153, 2021). "HDAC6 is considered a therapeutically important target for cancer treatment due to its interaction with proteins involved in cell growth, migration, protein degradation, and apoptosis." (PMID 34187263, 2021). "Pin1 upregulates HDAC6 expression through stabilization of HDAC6 mRNA and protein, which consequently promotes cell motility in cancer cells." (PMID 33807199, 2021). "It suggests that HDAC6 holds promise as a new drug target for anti-cancer immunotherapy or in combination with known immune checkpoint inhibitors to enhance immune infiltration and response to cancer." (PMID 34485153, 2021). "HDAC6 inhibitor therapy should ideally be used in the early stages of cancer promotion to block cancer proliferation and development by triggering autophagy leading to cancer cell death." (PMID 34944907, 2021). "First, as a primary analysis, we did not perform validation analysis on clinical samples or animal models, such as HDAC6 expression in multiple cancers." (PMID 34485153, 2021). "HDAC6 inhibitors are gradually being used in clinical drug development and are expected to be a new cancer treatment strategy." (PMID 34530730, 2021). "The dual inhibition of PI3K/HDAC6 is a promising strategy for the treatment of certain types of intractable cancers because of its advantages in overcoming potential resistance and producing synergistic effects." (PMID 33919077, 2021). "HDAC6 inhibits cilia formation, and HDAC6 inhibitors ricolinostat and citarinostat are currently being tested for cancer treatment." (PMID 34513696, 2021). "We focus on the controversy surrounding their ability to promote or block tumor progression and explore the impact of HDAC6 inhibitors on autophagy modulation in cancer." (PMID 34944907, 2021). "MiR‐22 has also been found to target many genes encoding cancer‐associated proteins, including the TET2 tumor suppressor, HDAC6, ERBB3, CDC25C, EVI‐1, and P21, which play different roles in different types of cancer." (PMID 33159388, 2021). "Plenty of of studies have indicated that blocking HDAC6/Hsp90 has a vital regulatory role in multifarious diseases, mainly in cancers." (PMID 34530730, 2021). "Considering the small number of normal sample data in TCGA, the expression of HDAC6 in each cancer in the TCGA and GTEx datasets was further integrated." (PMID 34485153, 2021). "We have discovered previously that the efficacy of ricolinostat (ACY-1215), a first-in-class orally available inhibitor of HDAC6, is significantly compromised in human cancer cells." (PMID 33807514, 2021). "MPT0B291, a novel selective inhibitor of HDAC6, demonstrated significant antiproliferative activity in various human cancer cell types." (PMID 34684020, 2021). "After analyzing GTEx, CCLE, and TCGA databases, we found that HDAC6 was differentially expressed in the TCGA database for pan-cancers." (PMID 34485153, 2021). "HDAC6 was investigated mainly in cancer development and treatment at first and was believed to strongly relate to oncogenic cell transformation, cancer immunity regulation, increased cell mobility and mitosis." (PMID 33744850, 2021). "In the present study, we analyzed immune infiltration and tumor immune microenvironment of HDAC6 in different cancers." (PMID 34485153, 2021). "In recent years, HDAC6-selective inhibitors have become an emerging class of cancer therapeutics, and several HDAC6-selective inhibitors have entered clinical trials." (PMID 33621955, 2021). "Previous reports have demonstrated that citarinostat characteristically inhibits the deacetylase activity of HDAC6 and induces apoptosis in human cancer cell lines." (PMID 33807514, 2021). "In conclusion, our results revealed a novel mechanism by which ABCB1 and ABCG2 actively transport citarinostat away from targeting HDAC6 in cancer cells." (PMID 33807514, 2021).
cancer (continued). "In this study, to observe the expression level of HDAC6 in pan-cancer, the expression of HDAC6 in various cancer databases was first analyzed." (PMID 34485153, 2021). "As expected, α-tubulin was typically deacetylated by the tubulin deacetylase HDAC6, and citarinostat promotes α-tubulin hyperacetylation in cancer cells by inhibiting the activity of HDAC6." (PMID 33807514, 2021). "A452 is a small-molecule inhibitor with a γ-lactam that selectively inhibits HDAC6 catalytic activity in various human cancer cells." (PMID 33572814, 2021). "We further confirmed that HDAC6 expression affected the expression of DNA repair genes and methyltransferases in pan-cancer." (PMID 34485153, 2021). "HDAC6 is differentially expressed in pan-cancers and plays an essential role in tumor metabolism and immunity." (PMID 34485153, 2021). "Since it is clear that recycling activity can benefit a system with a high rate of proliferation such as cancer, it is equally reasonable that HDAC6 works as the main actor in this signaling." (PMID 34944907, 2021). "Currently, more than a dozen HDAC6 inhibitors have been applied in the clinical treatment of cancer, which also proves that HDAC6 is a potential target molecule in clinical drug development." (PMID 34530730, 2021). "HDAC6 regulates the deacetylation of various substrates observed in many diseases, such as cancer and neurodegenerative disorders." (PMID 34944907, 2021). "By gene set enrichment analysis, we found that HDAC6 regulated signaling pathways related to cancer apoptosis and tumor immunity." (PMID 34485153, 2021). "On the other hand, several papers on cancer therapeutics suggest that autophagy can act to promote cell death of tumor cells in response to exposure to HDAC6 inhibitors." (PMID 35008169, 2021). "As most HDACs, HDAC6 regulates multiple biological pathways related to proliferation and development, and it is frequently deregulated in cancer, where its elevated levels promote tumor initiation and progression." (PMID 32488056, 2020). "HDAC6 was reported to regulate the autophagy process by regulating the acetylation level of α‐tubulin in neurodegenerative diseases, cancer and cardiomyocytes." (PMID 32885602, 2020). "The ability to specifically target HDAC6 would have valuable clinical utility in the treatment of these cancers." (PMID 32013157, 2020). "The results showed that both USP10 and HDAC6 expression were significantly (p < 0.01) increased in cancer patient samples compared to normal tissues." (PMID 32382008, 2020). "Histone deacetylase 6 (HDAC6) is an epigenetic modifier that is an attractive pharmacological target in cancer." (PMID 32488056, 2020). "In contrast, the expression of HDAC6 promoted colony and spheroid formation of cancer cells, as well as tumor growth in mice." (PMID 33114575, 2020). "Histone deacetylase 6 (HDAC6) is a unique histone deacetylating enzyme that resides in the cell cytoplasm and is linked to the modulation of several key cancer related responses, including cell proliferation and migration." (PMID 33322608, 2020). "Several studies have highlighted the role of histone deacetylase 6 (HDAC6) in various pathologies, including cancer." (PMID 32013157, 2020). "Rescuing HDAC6 or USP10 in USP10 knockdown cancer cells yielded a high survival rate and less PARP-1 cleavage." (PMID 32382008, 2020). "HDAC6 inhibitors are frequently used in preclinical studies in cancer because of their immunomodulatory properties." (PMID 33024443, 2020). "The fact that HDAC6 promotes migration and metastasis of cancer cells has made HDAC6 an interesting cancer drug target." (PMID 32888405, 2020).
cancer (continued). "Our previous work showed that epigenetic drugs including DNA methyltransferase inhibitors and histone deacetylase 6 inhibitors (DNMTis and HDAC6is) individually increase immune signaling in cancer cells." (PMID 32103105, 2020). "In agreement, the tubulin deacetylase HDAC6 seems to promote cell proliferation in several cancer cell lines, consistent with its upregulation in some cancers." (PMID 33114575, 2020). "In particular, HDAC6 knockout mice develop normally, which makes HDAC6 an ideal target in cancer treatment." (PMID 33020410, 2020). "On the other hand, HDAC6 inhibitors have notable anti-cancer properties in prostate cancer, breast cancer, melanoma, and ovarian cancer." (PMID 32013157, 2020). "Our results revealed that HDAC6, a promising target for cancer therapy, was inversely downregulated in HCC and uniquely endowed with tumor-suppressive activity by regulation CAMSAP2-mediated microtubule acetylation." (PMID 32206120, 2020). "The overexpression of HDAC6 in many cancer types led researchers to test the effects of HDAC6 inhibitors on these cancers." (PMID 32013157, 2020). "The anti-cancer effects of ACY-1215 is most frequently reported to result from the synergistic effect of HDAC6 inhibition with other drugs, such as inhibition with proteosomal pathway inhibitors." (PMID 33322608, 2020). "HDAC6 inhibition can enhance the efficacy of anticancer agents in cancers and suppress ESCC proliferation." (PMID 32357862, 2020). "The results of qRT-PCR (P < 0.001, n = 46) and Western blot (P < 0.01, n = 46) analyses revealed significant upregulation of HDAC6 in cancer tissues compared with paracancerous controls." (PMID 32107418, 2020). "Third, by inhibiting the expression of PD-1/PD-L1, HDAC6 inhibitors reinvigorate immune cell function, thereby promoting the killing of cancer cells by immune cells." (PMID 32676030, 2020). "Although HDAC6 seems to be an attractive pharmacological target in cancer, its expression has been only studied in small sets of cases for GBM so far18,19." (PMID 32488056, 2020). "Histone deacetylase 6 (HDAC6) belongs to the HDACs family and is prominently involved in carcinogenesis and cancer progression." (PMID 31901237, 2020). "By inhibiting HDAC6, they can promote the acetylation of α-tubulin thereby regulating cancer cell cycle and proliferation." (PMID 33262941, 2020). "In the future, further development of selective PROTAC E3 ubiquitin ligase degraders triggering HDAC6 degradation will provide further therapeutic options against various types of cancer, including CML." (PMID 32013157, 2020). "HDAC6 inhibition is a new therapeutic strategy against inflammation, cancer, and neurological disorders." (PMID 32973784, 2020). "Here, we aimed to study the role of HDAC6, which has been indicated important in many kinds of cancers, in EC diagnosis and therapy." (PMID 32107418, 2020). "ARID1A loss-of-function mutations sensitize cancer cells towards inhibition of EZH2, ATR, PARP, HDAC6, and HSP90 (and others)." (PMID 32272809, 2020). "This gap encouraged scientists to initiate serious attempts to identify new HDAC6 selective inhibitors to combat specific types of cancer." (PMID 31072216, 2019). "The synthesis of PET radiotracers for histone deacetylase 6 (HDAC6) has gained interest because of the possible involvement of this enzyme in cancer and various neuropsychiatric disorders." (PMID 31659516, 2019). "It has been reported that HDAC6-selective inhibition can bring on increased sensitivity of transformed cells to certain anti-cancer agents." (PMID 30782785, 2019).